SIRT7 (sirtuin 7)
Diseases named in the same sentence as SIRT7 in open-access papers (continued):
Sharing a sentence is not in itself a finding about the gene and the disease.
colorectal cancer (17 papers, 2015 to 2025). A primary or metastatic malignant neoplasm that affects the colon or rectum. "Similar observations were done in colorectal cancer cells where the overexpression of SIRT7 increased cell motility and invasiveness associated with an increase of mesenchymal markers." (PMID 29100388, 2017). "Consequently, loss or depletion of SIRT7 disrupts centromeric chromatin organization, promotes aneuploidy, and markedly increases susceptibility to colorectal cancer development in mice carrying predisposing oncogenic mutations." (PMID 41471367, 2025). "In colorectal cancer patients, SIRT7 level was significantly correlated with tumor stage, lymph node metastasis, and poor patient survival." (PMID 35585284, 2022). "SIRT7 also plays an important role in the development and progression of human colorectal cancer and functions as a valuable marker of colorectal cancer prognosis." (PMID 32953892, 2020). "In cervical cancer HDAC1, HDAC10, SIRT6, SIRT7 are always present; whist in colorectal cancer is HDAC10, SIRT6, SIRT7." (PMID 30691229, 2019). "Importantly, colorectal cancer patients with high SIRT7 expression exhibit decreased overall and disease-free survival." (PMID 26442981, 2015). "Besides, it has been shown that SIRT7 is involved in the development and progression of human colorectal cancer (CRC) and thus may serve as a novel prognostic marker and therapeutic target in CRC12." (PMID 26442981, 2015). "In colorectal cancer models, YZL-51N was shown to impair SIRT7-mediated double-strand DNA damage repair following ionizing radiation (IR), thereby enhancing the anti-tumor effect of IR in mouse xenograft models." (PMID 41471367, 2025). "Alternatively, SIRT7 deacetylates RAS-related nuclear protein (RAN), an event that promotes nuclear accumulation of STAT3 and subsequent autophagic response, inhibiting proliferation and metastasis of colorectal cancer cells." (PMID 37676263, 2024).
cardiac hypertrophy (16 papers, 2010 to 2024). "SIRT7 activity is associated with the pathology of the cardiovascular system in the form of heart failure, atherosclerotic changes, and myocardial hypertrophy, thus is considered a potential therapeutic target against cardiovascular and kidney diseases." (PMID 36614171, 2022). "Whilst SIRT6 has been implicated in the delay of ageing phenotype, DNA repair, and in the prevention of inflammation, ED and cardiac hypertrophy, SIRT7 is a major regulator of nuclear-encoded genes involved in mitochondrial function of cardiac cells." (PMID 29686722, 2018). "Loss of Sirt7 accelerates aging in mice, with cardiac hypertrophy, inflammatory response, and kyphosis." (PMID 28827661, 2017). "Sirt7-deficient mice develop progressive heart hypertrophy with an increased number of apoptotic cells in myocardium." (PMID 26070612, 2015). "Evidence has suggested that SIRT7 has a protective effect on cardiac hypertrophy, but its effect on cardiac fibrosis is inconsistent." (PMID 36581622, 2022). "Considering that there are few studies on SIRT7 in cardiac hypertrophy and fibrosis, further research is needed in the future." (PMID 36581622, 2022). "SIRT6 and SIRT7 were critical for heart development and repress cardiac hypertrophy via modulating histone acetylation and transcription factors." (PMID 33611744, 2021). "Studies have shown that Sirt1 can protect the heart from external stress, inflammation and cardiac hypertrophy; Sirt3 and Sirt7 in the heart of the stress response process also plays an extremely important role." (PMID 28582407, 2017). "To date, three family members—SIRT1, SIRT3, and SIRT7—havebeen shown to block stress-induced cardiac hypertrophy by impinging upon ROSgeneration." (PMID 20375467, 2010). "In addition, SIRT2, SIRT5, and SIRT7 have protective effects on cardiac hypertrophy, while SIRT4 appears to have the opposite effect." (PMID 36581622, 2022). "In addition, SIRT 1, 2, 6, and 7 reduce myocardial hypertrophy, and SIRT7 may prevent cardiomyopathy." (PMID 36614171, 2022).
pancreatic cancer (16 papers, 2015 to 2025). "In this study, we first provide evidence that the expression of SIRT7 is upregulated in pancreatic cancer tissues and associated with a poor prognosis." (PMID 35422493, 2022). "Both SIRT3 and SIRT7 appear to function as tumour suppressors in the context of pancreatic cancer; low levels of both proteins were associated with more aggressive tumour phenotypes and poorer patient outcome." (PMID 26121130, 2015). "In contrast to these, our results suggest that higher SIRT7 expression was associated with better prognostic markers in pancreatic cancer, including low tumour grade and R0 resections." (PMID 26121130, 2015). "Therefore, we endeavored to elucidate the underlying regulatory mechanism of SIRT7 by DDX3X in pancreatic cancer." (PMID 38316768, 2024). "Moreover, fasting mimicking protocols induced SIRT7 expression in pancreatic cancer cells, yet counterintuitively, SIRT7 deficiency augmented gemcitabine sensitivity by upregulating GLUT3 levels." (PMID 39682281, 2024). "Interestingly, our study, utilising a human resected pancreatic tumour TMA, investigated all seven sirtuins and has implicated SIRT3 and SIRT7 as being associated with more advanced pancreatic cancer." (PMID 26121130, 2015). "For instance, SIRT1 and SIRT7 were reported to promote pancreatic cancer progression, while SIRT2, SIRT4, SIRT5, and SIRT6 seem to play a tumor suppressor role." (PMID 41391757, 2025). "This suggests the possibility that SIRT7 potentially plays a crucial role in the initiation of pancreatic cancer." (PMID 38316768, 2024). "In summary, the exploration of SIRT7 as a therapeutic target in pancreatic cancer elucidates its multifaceted role in tumorigenesis and positions it as a pivotal player in developing innovative treatment strategies." (PMID 39682281, 2024). "Further investigations demonstrated that SIRT7 inhibits EMT in pancreatic cancer cells by transcriptionally repressing key target genes such as COL4A1 and SLUG, which are implicated in enhancing metastatic capabilities." (PMID 39682281, 2024). "A recent study reported that SIRT7 can become O-GlcNAcylated and stimulate pancreatic cancer progression." (PMID 38316768, 2024). "For instance, O-GlcNAcylation stabilizes the SIRT7 protein to promote the aggressiveness of pancreatic cancer by blocking the SIRT7–REGγ interaction." (PMID 37691108, 2023). "To determine the internal connection between SIRT7 and pancreatic cancer progression, we generated endogenous SIRT7 knockdown pancreatic cancer: PANC-1 and MiaPaCa-2 cells by shRNAs." (PMID 35422493, 2022). "We previously showed that higher expression of SIRT7 correlated with a worse prognosis of pancreatic cancer and promoted the progression of pancreatic cancer cells." (PMID 35422493, 2022). "SIRT7 can be O-GlcNAcylated and promotes pancreatic cancer progression by regulating its stability and deacetylation ability." (PMID 35422493, 2022). "Next, coimmunoprecipitation combined with subsequent MS was performed to identify O-GlcNAcylation as a potential novel PTM of SIRT7 by interaction with OGT in pancreatic cancer cell lines." (PMID 35422493, 2022). "One study found that patients with pancreatic cancer and high levels of nuclear SIRT7 had a longer lifespan (succumbed to disease later) than those with low levels of SIRT7." (PMID 30510540, 2018). "The exception is seen in pancreatic cancer, where SIRT7 is down-regulated and seems to act as a tumor suppressor." (PMID 30510540, 2018). "Our data suggests that SIRT3 and SIRT7 possess tumour suppressor properties in the context of pancreatic cancer." (PMID 26121130, 2015). "In addition, O-GlcNAcylation stabilizes Sirtuin 7 by inhibiting its interaction with proteasome activator subunit 3, and promotes pancreatic cancer progression." (PMID 40416363, 2025).
pancreatic cancer (continued). "Furthermore, O-GlcNAcylation can occur on SIRT7, which subsequently leads to enhancement of pancreatic cancer progression, as this modification regulates it its deacetylation potential and stability." (PMID 38316768, 2024). "The therapeutic modulation of SIRT7 through inhibitors that stabilize its expression and block pro-tumorigenic pathways may provide a novel approach to controlling pancreatic cancer progression, particularly in cases resistant to conventional therapies." (PMID 39682281, 2024). "SIRT7 inactivation in pancreatic cancer cells impaired their progression in vitro and in vivo." (PMID 35422493, 2022). "O-GlcNAcylation stabilizes the SIRT7 protein by inhibiting its interaction with REGγ to prevent degradation, and hyper-O-GlcNAcylation in pancreatic cancer cells leads to hypoacetylation of H3K18 via SIRT7, which promotes transcriptional repression of several tumour suppressor genes." (PMID 35422493, 2022). "Collectively, we demonstrate that O-GlcNAcylation is an important post-translational modification of SIRT7 in pancreatic cancer cells, and elucidating this mechanism of SIRT7 is expected to pave the way for the development of novel therapeutic methods in the future." (PMID 35422493, 2022). "The results indicated that OGT and SIRT7 interacted in the nucleus in pancreatic tumours." (PMID 35422493, 2022). "Moreover, SIRT7 may also contribute to the upregulation of PD-L1 in pancreatic cancer, but the supporting evidence remains limited, and the molecular mechanisms by which SIRT7 exerts these immunomodulatory effects in both malignancies are not yet delineated." (PMID 41471367, 2025). "Consequently, the development of SIRT7-based inhibitors may provide a novel strategy for enhancing treatment efficacy in pancreatic cancer, a malignancy characterized by its notorious resistance to conventional therapies and poor prognosis." (PMID 39682281, 2024). "Notably, SIRT7 expression is upregulated in pancreatic cancer cells, correlating with adverse prognostic outcomes and a heightened resistance to gemcitabine, a cornerstone of pancreatic cancer treatment." (PMID 39682281, 2024). "In sum, data suggest that SIRT7 may be a potential novel biomarker for prognosis in pancreatic cancer, a circulating marker in head and neck squamous cell carcinoma, and a predictive biomarker of pancreatic cancer (PCa) aggressiveness." (PMID 30510540, 2018). "Therefore, despite SIRT7 appearing to be involved in maintaining a tumourigeneic phenotype in perhaps breast or thyroid cancer, it has also the potential to possess anti-tumourigenic properties in pancreatic cancer." (PMID 26121130, 2015). "In pancreatic cancer cells, knockdown of SIRT7 resulted in increased expression of glucose transporter protein 3 (GLUT3) as well as increased levels of H3K122succ, which in turn led to pancreatic cancer cells being more sensitive to gemcitabine." (PMID 40867281, 2025). "Sirtuin 7 (SIRT7) inhibits the expression of GLUT3 by desuccinylating its H3 K122 residue, which subsequently decreases GEM uptake and confers resistance in pancreatic cancer." (PMID 40264038, 2025). "The results of our study indicate a positive relationship between SIRT7 mRNA and DDX3X mRNA in pancreatic cancer patient specimens." (PMID 38316768, 2024). "We next investigated the endogenous protein interaction by further exploring endogenous SIRT7 and OGT in pancreatic cancer cell lines." (PMID 35422493, 2022). "In this study, we demonstrate a connection between SIRT7 and OGT, providing an unexpected link between nutrient sensor O-GlcNAcylation and H3K18 acetylation in pancreatic cancer cells." (PMID 35422493, 2022). "We hypothesize that targeting SIRT7 might be beneficial for treating EGF signaling-dependent cancers, e.g., triple-negative breast cancers with increased EGFR expression and activity, colorectal and pancreatic cancers that harbor Ras mutations and NSCLCs with EGFR mutations." (PMID 34433808, 2021).
pancreatic cancer (continued). "In vivo analyses of pancreatic tumors from human and murine PDAC samples demonstrated colocalization of DDX3X and SIRT7, suggesting that SIRT7 may be subject to DDX3X regulation." (PMID 38316768, 2024).
glioma (15 papers, 2014 to 2025). A benign or malignant brain and spinal cord tumor that arises from glial cells (astrocytes, oligodendrocytes, ependymal cells). "Given the significant upregulation of SIRT7 in high-grade glioma and its association with poor patient prognosis, we next investigated the biological function of SIRT7 in glioblastoma cells using loss-of-function approaches." (PMID 41114868, 2025). "The SIRT family members (SIRT 1–7) are closely linked to carcinogenesis; carcinogenic roles of SIRT2 and SIRT7 have been documented in glioma and thyroid cancer, respectively." (PMID 25105144, 2014). "Even though SIRT7 has been implicated in tumorigenesis, the regulatory mechanisms of SIRT7 and the role of its upstream microRNAs in glioma progression remain unclear." (PMID 41114868, 2025). "Our data showed that SIRT7 is obviously expressed in glioma tissues and correlates with higher tumor grade and poorer prognosis, consistent with its oncogenic role." (PMID 41114868, 2025). "Our research results confirm that the miR-148a-3p/SIRT7 axis serves as a crucial modulator of glioma aggressiveness and the sensitivity of glioma cells to temozolomide (TMZ)." (PMID 41114868, 2025). "MiR-148a-3p, a regulatory microRNA, targets sirtuin 7, and its expression is significantly decreased in glioma tissues and cells, suggesting its role in regulating SIRT7 levels and influencing glioma progression and therapy response." (PMID 40710366, 2025). "We constructed SIRT7 knockdown and overexpression in glioma cells lines, and detected the tumor phenotypes." (PMID 41114868, 2025). "Overall, our discoveries identify the miR-148a-3p/SIRT7 axis as a vital mechanistic controller that manages both the progression of glioma and the sensitivity to chemotherapy with temozolomide." (PMID 41114868, 2025). "Considering the well-documented oncogenic function of SIRT7 in driving glioma progression, we next sought to investigate its upstream regulatory mechanisms." (PMID 41114868, 2025). "To validate these in - vivo findings and investigate the possible therapeutic uses of targeting SIRT7, we developed glioma xenograft models in nude mice." (PMID 41114868, 2025). "Our research indicated that SIRT7 is significantly over - expressed in tumor specimens obtained from glioma patients." (PMID 41114868, 2025). "SIRT7 is markedly overexpressed in higher-grade gliomas and contributes to cell proliferation, invasion, and chemoresistance through regulation of the ERK/STAT3 and IDH1-associated metabolic pathways." (PMID 40710366, 2025). "Experiments using siRNA to reduce SIRT7 expression in glioma cell lines resulted in decreased cell proliferation and invasion, suggesting that SIRT7 promotes glioma cell growth and spread." (PMID 40710366, 2025). "SIRT1, SIRT3, SIRT5, and SIRT7 are often overexpressed and promote glioma cell proliferation, stemness, therapy resistance, and metabolic adaptation." (PMID 40710366, 2025). "In glioma cells, SIRT7 knockdown leads to decreased IDH1 protein and mRNA levels, suggesting a positive regulatory role of SIRT7 on IDH1 expression." (PMID 40710366, 2025). "In this current study, we carried out a thorough analysis to understand the workings of the miR-148a-3p/SIRT7 molecular axis in glioma." (PMID 41114868, 2025). "Analysis of patient samples revealed a positive correlation between SIRT7 levels and glioma malignancy, with higher expression in grade IV gliomas compared with grade II gliomas, indicating its potential as a prognostic marker." (PMID 40710366, 2025). "Both the knockdown and overexpression of SIRT7 affect glioma cell proliferation, apoptosis, and cell cycle progression." (PMID 40710366, 2025). "Based on the results reported here, as well as previously published studies, we propose that activation of the KP in gliomas facilitates SIRT7-mediated recruitment of 53BP1 and subsequent repair of replication-associated strand breaks." (PMID 33870196, 2021).